OR2AG2 (olfactory receptor family 2 subfamily AG member 2)
Description:
Odorant receptor.
Synonyms: OR2AG2P; OR11-76
Tractability: Antibody: UniProt places it where antibodies can reach, with medium confidence; UniProt predicts a signal peptide or a membrane-spanning region; its Gene Ontology location is reachable by antibodies, with medium confidence.
Gene: Protein-coding gene on chromosome 11 (6,765,626 to 6,771,976, reverse strand). Ensembl gene ENSG00000188124.
Subcellular location: Cell membrane
Pathways (Reactome):
Sensory Perception: Expression and translocation of olfactory receptors
Gene Ontology:
Molecular function: olfactory receptor activity; G protein-coupled receptor activity
Biological process: detection of chemical stimulus involved in sensory perception of smell; G protein-coupled receptor signaling pathway
Cellular component: plasma membrane; membrane
Genetic constraint (gnomAD): Missense variants: 390 observed, 402.66 expected, observed/expected ratio (o/e) 0.97, 90% interval 0.89 to 1.05. Synonymous variants: 166 observed, 158.98 expected, observed/expected ratio (o/e) 1.04, 90% interval 0.92 to 1.19.
Homologues: Orthologues: chimpanzee OR2AG2 (98% identical), mouse Or2ag2 (82% identical), dog OR2AG1C (82% identical), dog OR2AG2 (82% identical), mouse Or2ag2b (80% identical), dog OR2AG2C (80% identical), rat Or2ag2 (80% identical), mouse Or2ag1 (80% identical), rat Or2ag2b (80% identical), rat Or2ag1 (79% identical), dog OR2AG1D (79% identical), mouse Or2ag18 (78% identical), and 16 more. Paralogues in human: OR2AG1 (87% identical), OR2T2 (50% identical), OR2T35 (50% identical), OR2T1 (49% identical), OR2T27 (49% identical), OR2T11 (48% identical), OR2T29 (48% identical), OR2T5 (48% identical), OR2AK2 (48% identical), OR2M3 (48% identical), OR2M2 (47% identical), OR2T4 (47% identical), and 80 more.
Diseases named in the same sentence as OR2AG2 in open-access papers:
OR2AG2 is named in the same sentence as 1 disease in open-access papers, as found by Europe PMC text mining. Sharing a sentence is not in itself a finding about the gene and the disease. The quoted sentences say what the papers report.
asthma (2 papers, 2019 to 2021). "A prioritized deleterious missense common variant in the olfactory receptor gene OR2AG2 that segregated with a risk haplotype in asthma, was validated in an asthma cohort of different ethnicity." (PMID 31836740, 2019). "Post bioinformatics analysis of exome sequencing and sequencing validation, a genetic variant from one candidate gene OR2AG2, encoding an olfactory receptor, was found in our multi-generational family to be novel in asthma." (PMID 31836740, 2019). "Out of the six disease co-segregating variants, the OR2AG2 genetic variant rs10839616 was found to be significantly associated with asthma (OR = 1.579, p = 0.0132; MAF = 0.42)." (PMID 31836740, 2019). "The hypothesis that asthma may be associated with decline in OR2AG2 was therefore explicitly tested in human samples and in-vitro experimental set up with IL-13 induction." (PMID 31836740, 2019). "To determine whether OR2AG2 genetic variations in the subjects were associated with altered olfactory function or other asthma-related phenotypes, we conducted subjective and objective testing." (PMID 31836740, 2019). "Together the data is consistent with a model where either innate genetic defects in OR2AG2 or acquired cytokine mediated suppression of OR2AG2 contributes to asthma pathogenesis." (PMID 31836740, 2019). "However, other possibilities cannot be excluded and the relevance of OR2AG2 in asthma genetics needs to be probed further." (PMID 31836740, 2019). "Our study suggests that OR2AG2 and other olfactory receptors may contribute to asthma pathophysiology." (PMID 31836740, 2019). "To validate our hypothesis, we compared the levels of OR2AG2 in RNA from lung lysates of asthma patients and normal subjects." (PMID 31836740, 2019). "Together the data supported the hypothesis that OR2AG2 may be a convergence point for asthma pathways at lung level." (PMID 31836740, 2019). "As an alternate explanation of similarity between asthmatic subjects with or without OR2AG2 variants, we hypothesized that OR2AG2 may be suppressed during molecular pathogenesis of asthma." (PMID 31836740, 2019).